CD4 (CD4 molecule)
Diseases named in the same sentence as CD4 in open-access papers (continued):
Sharing a sentence is not in itself a finding about the gene and the disease.
tumor (continued). "Th17 cells in tumor microenvironment are known to inhibit proliferation of CD4+ Th1." (PMID 36005179, 2022). "Therefore, PDT-OBBB can potentially stimulate the lymphatic traffic of the APCs into the dcLNs where the APCs activate the tumor antigens to the CD4+/CD8+ T cells." (PMID 36559105, 2022). "CD8+ T cell and CD4+ T cell infiltration were detected in tumours." (PMID 36195696, 2022). "However, upon CD4+ T cell activation or tumor cell proliferation, cells prefer the glycolysis-lactate production pathway even in the presence of oxygen." (PMID 35211629, 2022). "Splenic MDSCs from tumor-bearing mice showed a strong capacity to inhibit the proliferation of CD4+ T cells, while after cryo-thermal therapy, splenic MDSCs could promote the proliferation of CD4+ T cells at a high E/T ratio." (PMID 36389684, 2022). "Furthermore, PD-HPD patients show an increased amount of senescent CD4+ T cells (Tsens) and Ki67-positive effector regulatory T cells in tumor-infiltrating lymphocytes (TIL)." (PMID 36505821, 2022). "More recently, CD39 has been identified as a marker for tumor-specific CD4+ T cell population in human TILs suggesting that CD39 could be used to identify, isolate and expand tumor-reactive T cell population before ACT immunotherapy." (PMID 35008422, 2022). "Notably, slower growth correlated with increased expression of the CD4+ T cell ligand, HLA-DR, on the tumor cells themselves." (PMID 36419897, 2022). "While there are multiple regulators that have been identified, such as tumour-associated macrophages and myeloid-derived suppressor cells, in the context of ACT, a concerning mediator of the tumour microenvironment is CD4+ Tregs, which have been characterized as CD4+FOXP3+CD25+." (PMID 35158816, 2022). "Depletion of CD4 T cells only partially inhibited the effect of exoASO-STAT6 on tumor growth." (PMID 35179953, 2022). "To determine whether NSCLC tumor cells have the ability to directly present antigen to cytotoxic CD4+ T cells, we evaluated HLA expression in the CD45− cell fraction using scHLAcount50." (PMID 35831288, 2022). "The application of anti‐OX40 could promote tumor‐infiltrated CD4+ T‐cell proliferation and reduce the tumor metastasis." (PMID 35474948, 2022). "The same was seen in the tumor-infiltrating CD4+ and CD8+ T cells." (PMID 35566403, 2022). "Recent evidence shows that the susceptibility of CD4+ T-cells to HIV infection is intimately linked to their metabolic activity, with many of the metabolic features of HIV-1-infected cells resembling those found in tumor cells." (PMID 35205318, 2022). "Furthermore, CD4+ T cells exert their tumour-killing effect by secreting cytokines that activate CD8+ T cells." (PMID 36405713, 2022). "In mice, in which CD8 T cells are depleted, CD4 T cells can account for the slower tumor growth." (PMID 36611875, 2022). "Previously, we could show that infiltration of CD4+ T-cells in human PC specimens is significantly reduced compared with primary tumor samples." (PMID 35844581, 2022). "The authors hypothesized that CD4+ T cells partner with other innate cells, including natural killer (NK) cells and macrophages, to inhibit tumor growth." (PMID 36159781, 2022). "Moreover, CD4+ CD25highCD127low Tregs were up-regulated on tumor infiltrating T-cells from patients with GC compared to their expressions on corresponding peripheral blood and peritumoral T-cells." (PMID 34968167, 2022). "Thus, macrophage polarisation from the M2 to the M1 phenotype in the challenged tumour and a gradual increase in the levels of circulating CD4+ T cells were observed after administration of the combination therapy." (PMID 36211329, 2022). "CD3+CD4− T cells also comprise additional T cell subsets at low levels within the TME, most notably γδ T cells which are typically associated with favorable outcomes due to their roles in anti-tumor immunity alongside CD8+ TILs." (PMID 35804964, 2022).
tumor (continued). "Consequently, S1 + S2 stimulated OT-II CD4+ T cells were able to lyse B16-OVA tumor cells in vitro when cultured in Th1 media in a GzmB and MHC II dependent manner." (PMID 36241639, 2022). "Interestingly, despite the increased CD4 count in our case, the tumor size increased slowly for 1 year and subsequently began to shrink." (PMID 35141174, 2022). "Here, we performed HCC scRNA-seq data from the GEO database to define the cell subpopulations in tumours, and we found multiple subgroups of 5 cell types, including liver bud hepatic cells, CD4 + cytotoxic T cells, dendritic cells, Kupffer cells, and liver progenitor cells." (PMID 35078458, 2022). "Tumor-infiltrating CD4+ and CD8+ T cells were thus characterized using flow cytometric analysis." (PMID 36497232, 2022). "Additionally, in a tumor model, cDC2s induced CD4 T cell proliferation, and the generation of antitumor activity required depletion of regulatory CD4 T cells." (PMID 34480145, 2022). "It caused CD4+ and CD8+ T cells upregulation in the spleen, but downregulated immunosuppressive immune cells as regulatory T cells, myeloid-derived suppressor cells, and TAMs (tumor-associated macrophages) in the spleen and tumor tissues." (PMID 36080304, 2022). "On the one side, the Treg-depleting activity of anti-CTLA4 antibodies described in mouse models has not been replicated in human cancers and subsequent attempts of targeting tumor infiltrating Tregs by an anti-CCR4 antibody were limited by concomitant depletion of effector CD4+ and CD8+ T cells." (PMID 35874810, 2022). "Furthermore, other characteristics, such as CD4+ T cells, B cells, cytokines, and tumor-intrinsic oncogenic pathways, affect cancer prognosis." (PMID 35806328, 2022). "However, despite this reduced HRL expression, the numbers of CD8+ T cells per g of tumor in NK-depleted D7 tumors were significantly increased, and those of CD4+ T cells were trending toward an increase, while APC and myeloid populations were unchanged." (PMID 36531040, 2022). "In addition, Tregs secretes inhibitory cytokines such as TGF- β to weaken the anti-tumor effect mediated by CD4+T cells, CD8+T cells and NK cells." (PMID 36601120, 2022). "Furthermore, the development of tumor-specific adaptive immune responses, mediated by infiltrating CD4+ and CD8+ T lymphocytes, are driven by tumor antigens." (PMID 35326566, 2022). "Consequently, CD4+ T helper cells play a crucial role in tumor control as they enhance the activity of anti-tumoral effector cells." (PMID 36428793, 2022). "However, tumor-infiltrating CD4+ and CD8+ T cells showed much higher percentages of CD69, CCR5, and PDCD1 expression when compared with circulating T cells." (PMID 36301668, 2022). "We also demonstrated the presence of antigen-specific CD4+ Treg cells at tumor sites." (PMID 35309296, 2022). "However, studies on mice showed that the Th17 subpopulation was dominant in CD4+ T cells from TILs, and the population was also higher in the late tumor stages." (PMID 35954312, 2022). "With CD8+ cytotoxic and CD4+ helper T cells playing a central role in anti-tumor immunity, several PCTS-based studies have focused on understanding the localization and function of tumor infiltrating lymphocytes (TILs) in solid tumors, including lung, breast and melanoma." (PMID 35466279, 2022). "We noticed that IPD markedly increased the infiltration of total CD4+ T cells in tumor tissues." (PMID 36564797, 2022). "However, similar to their immunosuppressive actions towards TAMs and TANs, tumor cells often reduce activity of effector T cells and promote the recruitment of immunosuppressive CD4+ Tregs." (PMID 36230810, 2022). "Th1-polarized CD4+ T cells offer long-term protection against tumor rechallenge." (PMID 35874660, 2022). "Remarkably, depletion of CD4+ T cells in Asm-WT mice abolished tumor progression almost completely." (PMID 36426850, 2022). "Under the action of tumor cells, CD4 cells will produce specific immune tolerance." (PMID 35178106, 2022).
tumor (continued). "From the comprehensive data, we selected the three-day blood dataset, including six mice, from which the authors had described a mixture of CD4+ T cell clusters expanded by two different anti-tumor therapies, as revealed by a combination of Scaffold Maps and Citrus analysis." (PMID 35592315, 2022). "In addition to being directly cytotoxic to tumor cells, CD4+ T cells can mediate antitumor effects indirectly." (PMID 36159781, 2022). "Surprisingly, quantification of tumor-infiltrating lymphocytes per gram of tumor tissue revealed free and conducting treated oxRilac to be equally efficient in attracting CD4+ and CD8+ T cells to the tumor side with significant differences compared to untreated controls." (PMID 35892641, 2022). "We suggest that the cross-restriction of homocitrullinated peptide specific CD4 responses may pave the way to designing an effective universal anti-tumor vaccine." (PMID 35464453, 2022). "In 94 patients with OSCC, a higher density of CD3+ T cells in both the invasive margin (IM) and center of the tumor (CT) were associated with lower stage (T1 and T2 tumors) and increased CD8+ and CD4+ T cells in the invasive margin predicted lower risk of axillary metastases." (PMID 35937775, 2022). "Moreover, co-administration of IL-7 with tumor-reactive CD4+ T cells in a mouse model promotes their expansion, persistence and antitumor activity, corroborating the potential use of IL-7 as an adjuvant for CD4+ T cell-based ACT." (PMID 35008422, 2022). "In addition, IFN-γ attenuated Salmonella-stimulated immune responses by stimulating tumor infiltration by M1-like macrophages and CD4+ and CD8+ T cells, thereby facilitating tumor eradication." (PMID 36246355, 2022). "CD8+ T cells in the draining lymph nodes from tumor-bearing KO mice produced less IFN-γ than did those from tumor-bearing WT mice, whereas the frequencies of IFN-γ–producing CD4+ T cells in the draining lymph nodes were similar between tumor-bearing KO mice and tumor-bearing WT mice." (PMID 35143421, 2022). "With this background our finding that VEGFR3 inhibition induces upregulation of CD4+ T cells could indicate an important role in inhibiting tumor growth." (PMID 35681695, 2022). "Previous studies to date concerning IL-36 in tumorigenesis have predominantly focused on the effectiveness of IL-36R agonists in stimulating cells within the TME to favour tumour rejection by immune populations such as CD4+, CD8+ T cells and NK cell through activation and/or proliferation." (PMID 35365751, 2022). "Combining conventional immune checkpoint inhibition of CTLA‐4 and PD‐1 may enhance the Treg depletion within the tumor and further potentiate the CD4+ and CD8+ antitumor immunity." (PMID 35782339, 2022). "Therefore, we performed activated CD4+ T-cell/CD19+ B-cell/tumor cell coculture experiments to investigate the potential function of Bregs or sPD-L1 for immunotherapy." (PMID 35935985, 2022). "Primary tumor cells and tumor-associated macrophages (TAMs) from ovarian tumors produced CCL22, a ligand for CCR4, which was crucial for the migration Tregs, whose CCR4 expression was higher than other CD4+ T cells." (PMID 33603130, 2022). "Moreover, a more efficient antitumor effect to PD-1 inhibition and better tumor regression were presented owing to a higher CD8+/CD4+ ratio in bladder cancer." (PMID 36733388, 2022). "Chang’s study revealed that CD4+CD25+ Treg cells in the TME might rely on granzyme B and perforin to eliminate CD8+ effector T cells, resulting in a loss of function to help tumor cells escape from the toxic effect of CD8+ effector T cells." (PMID 36553542, 2022). "However, when administered in vivo to tumor-bearing C57BL/6 mice, they were able to modulate CD4 + CD25 + Foxp3+ T cells thus correcting the tumor-mediated immune-suppressive microenvironment." (PMID 35163063, 2022).
tumor (continued). "We found relative low proportions of CD4 T cells, B cells and plasma cells in tumor tissues, while high proportions of Treg, monocytes, thyrocytes, fibroblasts, and endothelial cells were seen in tumor tissues." (PMID 36387901, 2022). "However, possible differences in the function of CD4+ T cells within the tumour microenvironment, such as immune response activation or immunosuppression depending on the cancer type, can be one of the reasons." (PMID 36253752, 2022). "But, how the differentiation of CD4+ T cells is modulated and regulated by innate immune signaling pathways in DCs in the tumor microenvironment remains unclear." (PMID 35993548, 2022). "Additional analysis revealed that significant amounts of IL-2 could be produced by tumor-derived CD4+ and CD8+CD45RA- memory T-cells after combined anti-CD3/anti-CD28 stimulation." (PMID 35474089, 2022). "Thus, we initially sought to exploit our new tumor model to define the CD4 T cell compartment within the tumor and then utilize the single-cell transcriptomes to investigate how Tregs change within the tumor microenvironment over time." (PMID 35472220, 2022). "Th17 are a subset of CD4+ T cells characterized by the production of IL-17 and are also the key mediator of cancer development by their characteristic of both tumor-promoting and tumor-suppressing activities." (PMID 35053430, 2022). "Moreover, d-MAPPS inhibited generation of immunosuppressive phenotype in tumor-infiltrated CD4+ T cells." (PMID 35757015, 2022). "Although several studies have demonstrated that CD4 and CD8 have an immunological anti-tumor effect, there have been studies reporting the clinical importance of the CD4/CD8 ratio in tumor-infiltrating lymphocytes and their prognosis as a marker of the gastrointestinal tumor showing progression." (PMID 36326418, 2022). "Recent studies suggest that highly activated, polyfunctional CD4+ T cells are incredibly effective in strengthening and sustaining overall host antitumor immunity, promoting tumor-specific CD4+ T-cell responses and effectively enhancing antitumor immunity by immunotherapy." (PMID 35874660, 2022). "Effector CD4+ T cells and effector memory CD4+ T cells were the prominent clusters in the tumours." (PMID 35184398, 2022). "Furthermore, this Bregs subset was positively correlated with the frequency of CD4+CD25hi Tregs suggesting that they impact tumor progression through Tregs." (PMID 36618354, 2022). "As a result, using P-gp inhibitors in this situation is not advised because they may reduce the cytotoxic potential of tumour-infiltrating anti-cancer Th1 and Th17 CD4+T cell phenotypes." (PMID 35743927, 2022). "An altered tumor microenvironment signature was also identified in GC samples with MUC16 mutations; it was characterized by significantly decreased infiltration regarding stromal cells, CD4+ T cells, and macrophages." (PMID 35211490, 2022). "In a retrospective analysis of over 4000 PDAC tumor samples, mutant KRAS was seen in 81% of PDAC and was associated with higher M1 macrophages and cancer-associated fibroblast infiltration and lower CD4+/CD8+, natural killer (NK) cells, MSI-H status, and TMB compared to KRAS wild-type samples." (PMID 36290818, 2022). "The DCs then migrate from the tumor lesion to the nearest SLOs to present processed tumor-associated antigens (TAAs) on major histocompatibility complex class I (MHC I) and/or MHC II molecules to CD8+ and CD4+ T cells, respectively, thereby priming the T cells against neoplasm-specific antigens." (PMID 36713409, 2022). "Moreover, hypoxic tumor cell-released autophagosomes from human hepatocellular carcinoma cell line HepG2 induce more IL-10-producing B cells, with suppressive functions on CD4+ and CD8+ T cells." (PMID 36233088, 2022). "Next, we evaluated the role that tumor antigen presentation by bone marrow–derived myeloid cells to CD4 T cells might play on antitumor effect." (PMID 35903540, 2022).
tumor (continued). "We observed less tumor control in some of the mice in both groups at this CD4:CD8 ratio." (PMID 35422095, 2022). "With the increasing understanding of tumour immunity, studies have revealed that CD4+ T cells activated only by recognizing MHC class II antigen and activating the immune response of helper T cells play an important role in the antitumour activity of CD8+ effector T cells." (PMID 36016159, 2022). "This, in turn, suggests that CaMKK2 may restrict the abundance of CD40L+ IFNγ+ TNFa+ effector CD4+ TILs, the density of CD4+ cells per mm3 of tumor volume, and the tumor penetrance of CD4+ T cells." (PMID 36309495, 2022). "Cytotoxic CD8+ and helper CD4+ T cells play a critical role in eliciting an anti-tumor response." (PMID 36429128, 2022). "Therefore, it becomes important to discriminate tumor antigen–specific Th cells that persist in tumors from bystander CD4+ T cells that are recruited into the TME under proinflammatory conditions, but fail to be activated through their T cell receptor (TCR)." (PMID 35703176, 2022). "Two of the five T-cell infiltrated CAIX+ ccRCC tumors showed significant heterogeneity of intra-tumoral T-cell infiltration, with frequent CD8+ and CD4+ cells observed in some tumor regions with discrete CAIX expression but far fewer such cells in other contiguous CAIX-expressing areas." (PMID 36185254, 2022). "We next sought to investigate whether human PDAC cells can generate immunogenic tumor neo-antigens to be recognized by peptide-specific CD4+ T-cells." (PMID 35655709, 2022). "Furthermore, CD4+ T cells, via cytolytic mechanisms, are also capable of destroying tumor cells directly." (PMID 36138406, 2022). "When chimerism was established, we challenged the mice with tumor and transferred CD4 T cells." (PMID 35903540, 2022). "Moreover, the dysfunction of DC also attenuates CD4+ T-cell-mediated antitumor immunity responses, and inhibition of IL-6 reduces tumor growth by restoring T-cell activity in tumor-bearing mice." (PMID 36405719, 2022). "Similarly, there were trends toward a significant reduction in TIM-3 and LAG-3 expression on the surface of tumour-infiltrating CD4+ T cells post-FLOT and post-CROSS chemoradiotherapy." (PMID 35366537, 2022). "Of interest, INHBA expression was negatively correlated with infiltrating levels of activated NK cells, NKT, and CD4+ T cells but was positively correlated with tumor infiltration of CD8+ T cells, neutrophils, especially macrophages and cancer-associated fibroblasts." (PMID 36304286, 2022). "CD4 depleted mice lost most of the antitumor response, surviving barely 20 days, while CD8 depleted mice survived significantly longer, suggesting that CD4 T cells may have an additional role in tumor rejection besides helping CD8 T cells." (PMID 35903540, 2022). "Tumor-reactive CD4 TL have been found to ensure recruitment of cytotoxic CD8 TL at the tumor site." (PMID 35546670, 2022). "In addition, isolation of tumor antigen–specific CD4+ Th cells directly ex vivo, on the basis of cell-surface characteristics, would increase their potential for use in combined CD4+/CD8+ adoptive T cell therapy approaches." (PMID 35439168, 2022). "However, CRT containing both paclitaxel and cisplatin seems to have a positive effect on anti-tumor immunity by increasing the CD4+/CD8+ ratio and NLR ratio in the peripheral blood." (PMID 35566403, 2022). "The flow cytometry results showed significantly increased proportions of CD4+ and CD8+ T cells in the spleen, and the infiltration of CD4+ T cells was dramatically increased in the distant tumours by approximately threefold compared with that in the control group." (PMID 34731284, 2022). "Another mechanism by which CD4+ T cells can slow tumor growth is by inhibiting tumor angiogenesis." (PMID 36159781, 2022).